ROCK2 (Rho associated coiled-coil containing protein kinase 2)
Diseases named in the same sentence as ROCK2 in open-access papers (continued):
Sharing a sentence is not in itself a finding about the gene and the disease.
autoimmune disease (4 papers, 2019 to 2025). A disorder resulting from loss of function or tissue destruction of an organ or multiple organs, arising from humoral or cellular immune responses of the individual to their own tissue constituents. "ROCKs have been found to be involved in the pathogenesis of a variety of autoimmune diseases and a crucial role of ROCK2 in inflammatory bowel disease (IBD) has been reported." (PMID 39779619, 2025). "ROCK2 promotes Th17 cell differentiation and suppresses Treg differentiation, and abnormal activation of ROCK2 may be involved in the development of autoimmune diseases." (PMID 31655796, 2019).
Autoimmunity (4 papers, 2017 to 2024). The occurrence of an immune reaction against the organism's own cells or tissues. "The aberrant activation of ROCK2 in CD4+ T cells negatively affected its ability to phosphorylate, which suggested its potential to ameliorate pathogenic mechanisms in initiating autoimmunity." (PMID 38674328, 2024). "In another study, it was demonstrated that the inappropriate phosphorylation of IRF4 by ROCK2 downregulated production of IL-17 and IL-21 cytokines, which aggravated autoimmunity in mouse models." (PMID 38674328, 2024). "However, only the ROCK2 isozyme was shown to be physiologically activated in CD4+ T cells under T helper 17 (TH17) skewing and implicated in development of autoimmunity in mice." (PMID 30413785, 2018). "However, both the molecular mechanism as well as the specific contribution of ROCK2 to the development of autoimmunity is still enigmatic." (PMID 30413785, 2018).
endometriosis (4 papers, 2020 to 2025). The growth of functional endometrial tissue in anatomic sites outside the uterine body. "Moreover, overexpression of several genes including Cyp2r1, Fabp4, Mrc1, and Rock2 has been shown in the liver and visceral adipose tissue of endometriosis cases." (PMID 34806344, 2021). "Further researches were performed and found that inhibition of ERK signalling by PD98059 decreased the level of activated RhoA, total RhoA, ROCK1 and ROCK2, which implied ERK pathway might involve with the regulation of RhoA/ROCK pathway in endometriosis." (PMID 32725958, 2020).
Hyperglycemia (4 papers, 2013 to 2017). An increased concentration of glucose in the blood. "To test possible contribution of ROCK signaling pathway into hyperglycemia-induced impaired relaxation responses, we first treated diabetic endo(+) rings with ROCK2 inhibitor, 1-μM Y27632 and then they were contracted with 1-μM Phe." (PMID 23530857, 2013).
liver fibrosis (4 papers, 2012 to 2023). "In conclusion, our data demonstrate the complex mechanism underlying the reversal of established liver fibrosis by selective inhibition of ROCK2 in vivo." (PMID 37980369, 2023). "Recently, ROCK2 has been implicated in the regulation of pro-inflammatory pathogenic macrophages differentiation via STAT3/cofilin signaling pathways in the context of liver fibrosis in mice." (PMID 37980369, 2023). "This suggests that the highly selective ROCK2 inhibitor not only arrests the progression but promotes the reversal of existing liver fibrosis in vivo." (PMID 37980369, 2023). "Previously, it was demonstrated that ROCK2 inhibition attenuates profibrogenic immune cell function to reverse TAA-induced liver fibrosis in mice." (PMID 37980369, 2023). "Our study further verified the effect of carvedilol on the AT1R-mediated RhoA/ROCK2 pathway in mice with CCl4-induced liver fibrosis." (PMID 31828132, 2019). "Spironolactone lowers portal hypertension by improvement of liver fibrosis and inhibition of intrahepatic vasoconstriction via down-regulating ROCK-2 activity and activating NO/PKG pathway." (PMID 22479572, 2012). "Thus, potent ROCK2 inhibition is required to ameliorate established liver fibrosis induced by chemical injury in the settings of metabolic dysregulation, which is reminiscent of patients with NASH." (PMID 37980369, 2023). "Therefore, the newly discovered triple effect of selective ROCK2 inhibition to target convergently pro-inflammatory, fibrotic, and metabolic pathways in vivo underscores the integral role of ROCK2 signaling in regulation of liver fibrosis." (PMID 37980369, 2023). "Here we show that therapeutic administration of GV101, a selective ROCK2 inhibitor with more than 1000-fold selectivity over ROCK1, attenuates established liver fibrosis induced by thioacetamide (TAA) in combination with high-fat diet in mice." (PMID 37980369, 2023). "Here we characterize a highly ROCK2-specific inhibitor, GV101, which efficiently treats established liver fibrosis in mice." (PMID 37980369, 2023). "In this study, we report that a highly selective ROCK2 inhibitor, GV101, attenuates established liver fibrosis in mice induced by chemical injury alone or in combination with a high fat, so called Western diet." (PMID 37980369, 2023).
lupus (4 papers, 2016 to 2023). "T cells from MRL/lpr mice, a spontaneous model of lupus, also display aberrant activation of ROCK2, and ROCK inhibition diminishes theirin vitro production of IL-17 and IL-2123." (PMID 27785353, 2016). "Subsequently, ROCK2 was found to be selectively activated in murine lupus T cells." (PMID 30524430, 2018). "In these lupus models, ROCK2 regulates IRF4 and increases IL-17 and IL-21 production." (PMID 30524430, 2018).
omphalocele (4 papers, 2012 to 2022). Omphalocele is an embryopathy classified in the group of abdominal celosomias and is characterized by a large hernia of the abdominal wall, centered on the umbilical cord, in which the protruding viscera are protected by a sac. "ROCK1 knockout (KO), ROCK2 KO, and ROCK1/2 double heterozygous mice has been reported to exhibit omphalocele phenotype due to disorganization of actin filament in the epithelial cells of umbilical ring." (PMID 29555972, 2018). "When these ROCK2–/– mice were backcrossed into a C57BL/6 genetic background, they exhibit not only the placental phenotype but also perinatal EOB and omphalocele phenotype, indicating that genetic background affects the EOB and omphalocele phenotype in ROCK2–/– mice." (PMID 35043239, 2022).
age-related macular degeneration (3 papers, 2018 to 2021). Age-related loss of vision in the central portion of the retina (macula), secondary to retinal degeneration. "In addition, ROCK2 plays a key role in macrophage polarization into proinflammatory macrophage type 1 in age-related macular degeneration model." (PMID 34443331, 2021).
Anxiety (3 papers, 2021 to 2025). Intense feelings of nervousness, tension, or panic often arise in response to interpersonal stresses. "Rock2, a serine/threonine kinase, takes part in actin cytoskeleton organization, and its deletion has been linked to anxiety-like behavior and the alteration of dendritic spine density and morphology in the hippocampus." (PMID 36675068, 2023). "This suggests that the neurobiological mechanisms driving the anxiety-like behaviors in ROCK2+/− mice remain to be fully elucidated." (PMID 34794469, 2021). "Previous work indicated that adult male and female ROCK2+/− mice displayed anxiety-like behaviors on the elevated plus maze (EPM) compared to ROCK2+/+ littermates, which was similar to wild-type mice that were treated with the pan-ROCK inhibitor Fasudil for 30 days." (PMID 34794469, 2021). "Based on the analogous EPM phenotypes under pharmacologic pan-ROCK inhibition, ROCK2 heterozygosity, or conditional deletion of ROCK2 herein, we hypothesize that disruption of ROCK2’s function in forebrain excitatory neurons drives anxiety-like behavior in mice." (PMID 34794469, 2021). "However, it is also possible that projections from the vCA1 to the lateral hypothalamic area (LHA), but not to the BLA, is modulating the anxiety-like behavior in ROCK2 deficient mice." (PMID 34794469, 2021).
breast tumor (3 papers, 2015 to 2024). "Based on gene expression data from TCGA project, we found that ROCK2 expression was positively correlated with BRCA2 expression in breast tumor donors while there is no such correlation in normal breast tissue." (PMID 39013885, 2024).
colitis (3 papers, 2021 to 2023). Inflammation of the colon. "In control animals, Mapk9 mRNA was upregulated in the colon due to the absence of Muc13 expression, whereas the mRNA levels of Mapk1, Mapk9, Rock2 and Snai1 were also affected upon acute colitis in Muc13−/− mice compared to their wildtype counterparts." (PMID 37174625, 2023). "The expression of RhoA, ROCK1 and ROCK2 was significantly increased in colitis." (PMID 36189321, 2022). "However, continuous treatment with NaHS from day one after colitis decreased the expression of RhoA, ROCK1, and ROCK2 proteins in CSE KO and WT mice." (PMID 36189321, 2022). "Therefore, it is not surprising that colitis-induced RhoA, ROCK1, and ROCK2 expression levels were even higher in CSE KO mice than in WT mice." (PMID 36189321, 2022).
epilepsy (3 papers, 2022 to 2025). A brain disorder characterized by episodes of abnormally increased neuronal discharge resulting in transient episodes of sensory or motor neurological dysfunction, or psychic dysfunction. "By elucidating the mechanisms of action underlying these effects, we can better leverage ROCK2 inhibitors for targeted therapies in epilepsy." (PMID 40878444, 2025). "This study provides novel insights into the genetic and molecular mechanisms driving epileptic network dysfunction and highlights ROCK2 as a compelling target for translational epilepsy research." (PMID 40878444, 2025). "While the neuroprotective role of ROCK2 inhibition in epilepsy has been previously acknowledged, this study is the first to establish a direct link between ROCK2 inhibition, enhanced mitophagy, and synapse protection." (PMID 40878444, 2025). "Y-27632, a ROCK inhibitor, reduces hippocampal RhoA and ROCK2 expression in KA-induced epilepsy mice, while Y- 27,632 also facilitated neurite formation in excitotoxicity by glutamate in vitro." (PMID 35119588, 2022). "To validate ROCK2 as a therapeutic target for TLE, we established pilocarpine‐induced acute TLE mouse models and randomly assigned mice into two groups: one group received the ROCK2 inhibitor belumosudil (the ROCK2 group), and the other received saline as a control (the epilepsy model (EP) group)." (PMID 40878444, 2025). "Given its selectivity for ROCK2, established in vivo efficacy, and pharmacokinetic stability, belumosudil represents a promising candidate for modulating aberrant synaptic networks in epilepsy." (PMID 40878444, 2025). "The results suggested that the MEL‐mediating regulation of RhoA/ROCK2 signaling pathway might be a potential important target in the treatment of epilepsy." (PMID 37382264, 2023). "Accordingly, we propose that the neuroprotective effects of ROCK2 inhibition in epilepsy are mediated, at least in part, through the enhancement of neuronal mitophagy, providing a mechanistic basis for its role in modulating both synaptic networks and the progression of epilepsy." (PMID 40878444, 2025).
fibrosis (3 papers, 2020 to 2024). the formation of excess fibrous connective tissue in an organ or tissue in a reparative or reactive process. "Taken together, these results suggested that IGF-1 inhibited AngII-induced cardiac fibrosis through Akt-dependent and ROCK2- associated pathways." (PMID 34244467, 2021). "In non diabetic mice, double ROCK knockout promotes cardiac autophagy and fibrosis, whereas in ROCK2 knockout mice, autophagy is inhibited and increased cardiac fibrosis is observed." (PMID 32375786, 2020).
Insulin resistance (3 papers, 2018 to 2022). Increased resistance towards insulin, that is, diminished effectiveness of insulin in reducing blood glucose levels. "Partial deletion of ROCK2 in mice also decreased adipose tissue remodeling associated with decreased HFD-induced adipose and systemic insulin resistance." (PMID 35769086, 2022). "Although these studies established a role for hepatic ROCK1 in promoting adiposity, insulin resistance, and hepatic lipid accumulation, the role for hepatic ROCK2 in regulating these metabolic functions remains to be explored." (PMID 35769086, 2022).
lymphedema (3 papers, 2024 to 2025). Excess fluid collection in tissues, causing swelling. "Based on these findings, a lymphatic-specific ROCK2 inhibitor was used in an in vivo murine lymphedema model." (PMID 38726373, 2024). "It was found that the ROCK2 inhibitor decreased tail swelling indicating a reversal of the induced lymphedema." (PMID 38726373, 2024). "Lymphatic-specific knockdown of ROCK2 reverses lymphedema in vivo and could serve as a potential therapeutic target for lymphedema." (PMID 40766782, 2025).
Parkinson disease (3 papers, 2024 to 2025). A progressive degenerative disorder of the central nervous system characterized by loss of dopamine producing neurons in the substantia nigra and the presence of Lewy bodies in the substantia nigra and locus coeruleus. "SR3677, a selective drug inhibitor of ROCK2, was investigated for its role in modulating mitophagy in a Parkinson’s disease model." (PMID 40143028, 2025). "Several reported studies suggests that ROCK2 may serve as a therapeutic target for treating neurodegenerative disorders such as Huntington’s disease (HD), Parkinson’s disease (PD), and Alzheimer’s disease." (PMID 40359277, 2025).
portal hypertension (3 papers, 2012 to 2023). Increased blood pressure in the portal venous system. "We further uncovered a previously unappreciated integral anti-inflammatory and anti-metabolic effect of ROCK2 inhibition in human monocytes and Kupffer cells, two types of innate immune cells that actively contribute to liver disease progression." (PMID 37980369, 2023). "It is well known that in cirrhosis activated RhoA/ROCK-2 signaling and inhibited nitric oxide (NO) availability contribute to increased intrahepatic resistance and portal hypertension." (PMID 22479572, 2012). "Moreover, carvedilol inhibited Ang II-induced HSC contraction by interfering with the AT1R-mediated RhoA/ROCK2 pathway, which may be one of its molecular mechanisms for reducing portal hypertension." (PMID 31828132, 2019). "Therefore, the aim of the present study was to investigate the effect of chronic spironolactone treatment on intrahepatic RhoA/ROCK-2 signaling and NO/PKG pathway as well as on lilver fibrosis and portal hypertension." (PMID 22479572, 2012).
preeclampsia (3 papers, 2014 to 2018). Preeclampsia is a hypertensive disorder of pregnancy that is characterized by new-onset hypertension with proteinuria presenting after 20 weeks of gestation, and depending on mild or severe forms may initially present with severe headache, visual disturbances, and hyperreflexia. "Finally, we investigated the presence of variants in four selected genes previously reported in relation to preeclampsia; the ROCK2, ACVR2A, ERAP1, and ERAP2 genes." (PMID 29758065, 2018). "Predicted deleterious variants in ROCK2, AVCR2A, ERAP1, and ERAP2 in women with (cases) and without (controls) preeclampsia." (PMID 29758065, 2018). "Although expression of ROCK1 and ROCK2 was not different, a higher RhoA mRNA expression was found in placentae from women who suffered from preeclampsia compared with placentae from those that were normotensive." (PMID 25628539, 2014).
Sepsis (3 papers, 2024 to 2025). Sepsis is defined as life-threatening organ dysfunction caused by a dysregulated host response to infection. "Circ_0114428 and ROCK2 expression were significantly increased, but miR-574-5p was decreased in blood samples from sepsis patients and LPS-stimulated HPAEpiCs." (PMID 38297223, 2024). "As revealed by Spearman correlation analysis, miR-574-5p was negatively correlated with ROCK2 in expression in the blood samples of sepsis patients." (PMID 38297223, 2024). "Circ_0114428 knockdown protected against LPS-induced HPAEpiC injury through miR-574-5p/ROCK2 axis, providing a novel therapeutic target in sepsis-induced ALI." (PMID 38297223, 2024). "Comparatively, ROCK2 was significantly upregulated in the blood samples of sepsis patients and LPS-treated HPAEpiCs." (PMID 38297223, 2024). "Hydrogen-induced inhibition of ALI in sepsis mice involved ROCK2." (PMID 38297223, 2024). "In this work, sepsis patients and LPS-treated lung cells showed a high expression of ROCK2." (PMID 38297223, 2024). "Similarly, Salvia miltiorrhiza constituents exert organ-protective effects: tanshinone IIA ameliorates sepsis-induced lung injury by downregulating ROCK2 and inactivating NF-κB, while salvianolic acid B attenuates hepatic and renal injury via antioxidant and anti-apoptotic mechanisms." (PMID 41357500, 2025).
type 2 diabetes (3 papers, 2014 to 2022). "We will further focus on the effect of ROCK2 inhibition on type 2 diabetes mice in a follow-up study." (PMID 35865967, 2022).
allergic asthma (2 papers, 2023 to 2025). A asthma with a basis in a pathological type I hypersensitivity reaction. "In conclusion, this descriptive and exploratory study identifies, for the first time, an association between the RG1 protein and AHR in a guinea pig model of allergic asthma, alongside the concomitant overexpression of ROCK2." (PMID 41463119, 2025). "Thus, high expression of PIAS1 in bronchial epithelia of the patients and mouse model with allergic asthma promoted the SUMOylation and activation of ROCK2 and thereby induced the airway goblet cell metaplasia." (PMID 37393345, 2023). "The observed overexpression of RG1 in the allergic asthma guinea pig model is positively associated with AHR and with ROCK2, suggesting a possible functional interaction with the MLCP pathway, primarily with MYPT1, which could influence the modulation of smooth muscle contractility." (PMID 41463119, 2025).
angiosarcoma (2 papers, 2016 to 2017). A malignant tumor arising from the endothelial cells of the blood vessels. "We analyzed the proliferation rates of scrambled control and ROCK2 shRNA knockdown xenograft angiosarcoma tumors using immunohistochemical staining for the proliferative marker Ki67." (PMID 28709411, 2017). "A decreased cell migration rate was observed with either ROCK1 or ROCK2 knockdown in mouse pancreatic endothelial cells and angiosarcoma cells, only ROCK2 knockdown showed reduced phosphorylation of MLC phosphatase and cofilin." (PMID 26725045, 2016). "ROCK2 protein is significantly increased in benign vascular tumors including capillary and cavernous hemangiomas, as well as malignant hemangioendotheliomas, hemangiopericytomas, and angiosarcomas." (PMID 28709411, 2017). "Our findings revealed that ROCK1 was overexpressed in malignant vascular tumors such as hemangioendotheliomas and angiosarcomas, and ROCK2 was overexpressed in both benign and malignant vascular tumors including hemangiomas, hemangioendotheliomas, hemangiopericytomas, and angiosarcomas." (PMID 28709411, 2017).
autoimmune myocarditis (2 papers, 2020 to 2024). Autoimmune myocarditis is an autoimmune disease that affects the heart. "In this study, using wild-type, Rock1+/− and Rock2+/− haploinsufficient mice and mouse model of experimental autoimmune myocarditis (EAM) we addressed the role of ROCK1 and ROCK2 in development of myocarditis and postinflammatory fibrosis." (PMID 32178482, 2020). "In this study, we also addressed their contribution also to the development of autoimmune myocarditis and found that Rock1+/− and Rock2+/− developed unaffected CD4+ T cell-mediated cardiac inflammation." (PMID 32178482, 2020). "However, neither ROCK1 nor ROCK2 participated in the progression of fibrosis in the experimental autoimmune myocarditis mouse model study." (PMID 39455522, 2024).